ACTRT3 (actin related protein T3)
Synonyms: ARP-T3; ARPM1
Tractability: No criterion of Open Targets' tractability assessment is met for any kind of drug.
Gene: Protein-coding gene on chromosome 3 (169,765,610 to 169,769,665, reverse strand). Ensembl gene ENSG00000184378.
Subcellular location: Cytoplasm, cytoskeleton; Cytoplasm; Nucleus
Subcellular location (Human Protein Atlas): Nucleoplasm; Acrosome; Centrosome; Cytosol
Gene Ontology:
Molecular function: protein binding; structural constituent of cytoskeleton
Biological process: cytoskeleton organization
Cellular component: actin cytoskeleton; perinuclear theca; cytoplasm; cytoskeleton; male germ cell nucleus; nucleus
Genetic constraint (gnomAD): Loss-of-function variants: 21 observed, 24.34 expected, observed/expected ratio (o/e) 0.86, 90% interval 0.61 to 1.24. The upper end of that interval is the gene's LOEUF score, 1.24, which puts it in group 5 of 6, group 1 being the genes least tolerant of losing a copy. Missense variants: 457 observed, 493.99 expected, observed/expected ratio (o/e) 0.93, 90% interval 0.86 to 1. Synonymous variants: 169 observed, 186.68 expected, observed/expected ratio (o/e) 0.91, 90% interval 0.8 to 1.03.
Homologues: Orthologues: chimpanzee ACTRT3 (99% identical), macaque ACTRT3 (96% identical), rabbit ACTRT3 (85% identical), pig ACTRT3 (85% identical), dog ACTRT3 (84% identical), guinea pig ACTRT3 (80% identical), mouse Actrt3 (79% identical), rat Actrt3 (78% identical). Paralogues in human: ACTG1 (50% identical), ACTB (50% identical), ACTA1 (49% identical), ACTA2 (49% identical), ACTC1 (49% identical), ACTG2 (49% identical), ACTBL2 (48% identical), ACTRT2 (46% identical), ACTRT1 (43% identical), ACTR1A (42% identical), ACTR1B (42% identical), ACTR2 (37% identical), and 14 more.
Diseases named in the same sentence as ACTRT3 in open-access papers:
ACTRT3 is named in the same sentence as 2 diseases in open-access papers, as found by Europe PMC text mining. Sharing a sentence is not in itself a finding about the gene and the disease. The quoted sentences say what the papers report.
melanoma (1 paper, 2017). A malignant, usually aggressive tumor composed of atypical, neoplastic melanocytes. "The results also included 10 SNPs previously identified for melanoma risk reported at MC1R (2 SNPs), MX2, TERT/CLPTM1L, PLA2G6, CASP8, ACTRT3, ASIP, CDC91L1, and ARNT/SETDB1/LASS2ANXA9/MCL1/CTSK." (PMID 27993549, 2017).
ACTRT3 also shares sentences with these, for which no sentence is quoted: tumor (1 paper).